CDC73 (cell division cycle 73)
Diseases named in the same sentence as CDC73 in open-access papers (continued):
Sharing a sentence is not in itself a finding about the gene and the disease.
parathyroid disease (6 papers, 2008 to 2025). "The surveillance program for prototypic tumors of MEN1 in our patient's family did not change in terms of including imaging to prototypic tumors of carriers of CDC73 mutations other than parathyroid disease, as the CDC73 variant detected in some family members is probably benign." (PMID 34889280, 2021). "We are confident that it may help in the identification of subjects at risk to have a CDC73 gene mutation and consequently at risk to develop an aggressive parathyroid disease on the basis of a patient’s blood sample test." (PMID 29755684, 2018). "Using NGS, we identified three pathogenic variants in two genes (CDC73 and MEN1), 10 likely pathogenic variants in six genes (CASR, CDC73, LRP5, MEN1, SDHA, and VHL), and 39 non-synonymous VUS variants that could be related to parathyroid disease." (PMID 35586626, 2022). "Both oncogenes and tumor suppressor genes, such as MEN1 and CDC73 (previously named HRPT2), are involved in parathyroid disease pathogenesis." (PMID 35628190, 2022).
uterine neoplasms (6 papers, 2017 to 2025). "On the other hand, in vivo animal models found that heterozygote CDC73 variant was associated with uterine neoplasms in mice." (PMID 38396977, 2024). "The screening for CDC73 germline mutations is indicated in presence of familial pHPT, in case of pHPT with young age onset (<40 years), multiglandular involvement, cystic, atypical, or malignant parathyroid involvements, or in presence of coexistence ossifying jaw fibroma, renal, or uterine tumors." (PMID 31929790, 2019). "Mice with CDC73 knockout in the parathyroid develop parathyroid and uterine tumors and are used as a model for HPT-JT syndrome." (PMID 36211470, 2022). "Parafibromin expression was present in uteri of ⩾18 month old Cdc73+/+ mice, but was reduced in uterine tumours (for example, fibroadenoma) of Cdc73+/− mice." (PMID 28288139, 2017). "Uterine neoplasms, myometria and jaw bones of Cdc73+/− mice had increased proliferation rates that were 2-fold higher than in Cdc73+/+ mice (P<0.05)." (PMID 28288139, 2017). "This was confirmed by immunostaining for Ki-67, which revealed a significantly increased proliferation in the endometria and myometria of Cdc73+/− mice with uterine tumours, by 1.5- and 2.5-fold, respectively, when compared to equivalent uterine tissues of wild-type littermates." (PMID 28288139, 2017). "Thus, Cdc73+/− mice provide an in vivo model for the study of APAs and uterine neoplasms." (PMID 28288139, 2017). "Cdc73+/− mice did not develop bone or renal tumours but female Cdc73+/− mice, at 18 months of age, had uterine neoplasms comprising squamous metaplasia, adenofibroma and adenomyoma." (PMID 28288139, 2017). "Macroscopic uterine tumours at necropsy were observed in 33.3% (n=8/24) of female Cdc73+/− mice, aged ⩾18 months, but in none of 24 Cdc73+/+ littermates (P<0.005, two-tailed Fisher’s exact test)." (PMID 28288139, 2017).
breast carcinoma (5 papers, 2016 to 2025). "Genetic testing (including breast cancer susceptibility genes) confirmed that the familial CDC73 c.1155-3A > G variant was present." (PMID 39677927, 2025). "According to the data from KM plotter, CDC73 mRNA expression was negatively linked to the high overall, relapse-free and post-progression survival rates of the patients with breast cancer (p<0.05)." (PMID 29221126, 2017). "Expression of CDC73 is also negatively associated with the progression of breast cancer patients." (PMID 35551175, 2022). "In addition, low CDC73 expression is significantly associated with poor relapse free survival of breast cancer patients (p = 0.0017), particularly lymph node-positive breast cancer patients (p = 0.00042)." (PMID 35551175, 2022). "In addition, low expression of CDC73 has also been found associated with adverse pathological parameters in human breast cancer cases." (PMID 35551175, 2022). "Interestingly, the expression level of CDC73 is positively associated with the infiltration level of CD8+ T cells in human breast cancer (p = 1.59 × 10−13)." (PMID 35551175, 2022). "Notably, clinical metadata analyses in this study validate that low expression of CDC73 is associated with poor relapse free survival of breast cancer patients, as well as decreased levels of tumor-infiltrating CD8+ T cells." (PMID 35551175, 2022). "The result shows that the mRNA level of CDC73 is significantly lower in breast cancer than that in normal breast tissues (p = 1.889 × 10−5) and lower still in TNBC than other breast cancer subtypes (p = 0.002)." (PMID 35551175, 2022). "We analyzed publicly available human patient-derived data from the Gene Expression Omnibus database (subset GSE42568 and GSE76275) to assess the expression level of CDC73 in human breast cancer." (PMID 35551175, 2022). "CDC73 expression was negatively correlated with post-progression survival rate of Luminal-A breast cancer patients, or distant-metastasis-free survival rate of PR-positive breast cancer patients respectively (p<0.05, data not shown)." (PMID 29221126, 2017). "Genetic testing that identified the germline CDC73 variant included a breast cancer panel but did not identify any other variants." (PMID 39677927, 2025). "Interestingly, our results also showed that UBR5 can not only down-regulate the expression of the CDC73 in breast cancer cells, but also additional PAF1C subunits PAF1, CTR9, and LEO1." (PMID 35551175, 2022). "Furthermore, we investigated the correlation of the mRNA expression between CDC73 and several crucial immune response regulators that are involved in regulating T cell activation in human breast cancer." (PMID 35551175, 2022). "Clinical metadata analysis demonstrates a strong negative association of CDC73 expression with relapse free survival of breast cancer patients." (PMID 35551175, 2022). "CDC73 mRNA expression was positively related to both overall and progression-free survival rates of the patients with gastric cancer, even stratified by gender, lymph node involvement, or treatment (p<0.05), while versa for breast cancer (p<0.05)." (PMID 29221126, 2017). "In breast cancer, there was a negative association of CDC73 expression with the overall, relapse-free, post-progression or distant-metastasis-free survival rates of the patients, even in the subgroups." (PMID 29221126, 2017). "The molecular switch role of CDC73 in inhibiting UBR5’s pro-tumor capacities points to a novel potential therapeutic target and strategy for immune therapy of breast cancer." (PMID 35551175, 2022). "Hence, CDC73/PAF1C might be a potential target for developing targeted breast cancer therapies." (PMID 35551175, 2022).
breast carcinoma (continued). "CDC73 could serve as a molecular switch to modulate UBR5’s pro-tumor activities and may provide a potential approach to developing breast cancer therapeutic interventions." (PMID 35551175, 2022). "We predicted that 6 genes including ANXA1 would be regulated by miR196a using 4 prediction softwares (TargetScan, MiRanda, Diana MicroT and PicTar), and confirmed the reduction of these genes (ANXA1, HOXA7, HOXB7, ING5, CDC73 and SMURF1) by miR-196a in breast cancer cells using qPCR analysis." (PMID 27105503, 2016). "Hence, one might seek to enhance tumor suppressor CDC73’s stability in cancer cells by maintaining its phosphorylated state, thus inhibiting its ubiquitination and degradation mediated by UBR5, as a potential therapeutic strategy for breast cancer patients with low CDC73 levels." (PMID 35551175, 2022).
Hypercalcemia (5 papers, 2017 to 2023). An abnormally increased calcium concentration in the blood. "In one of these studies it was suggested that early onset and severe hypercalcemia (> 3 mMol) may be predictive factors for a possible CDC73 genetic lesion, independently from the clinical diagnosis (HPT-JT or FHIP or PC)." (PMID 29755684, 2018). "Genetic testing for mutations in the CDC73 (HRPT2) gene was negative; MEN‐1 mutations were not evaluated due to the absence of evidence of other associated tumors or familial history of hypercalcemia or MEN‐1‐associated tumors." (PMID 32884778, 2020).
gastric cancer (4 papers, 2017 to 2022). A primary or metastatic malignant neoplasm involving the stomach. "Taken together, we concluded that CDC73 mRNA underlay the molecular mechanisms of the differentiation of gastric cancer." (PMID 29221126, 2017). "Mutation of these residues to phenylalanine stabilizes the CDC73 interaction with β-catenin and enhances WNT signaling in gastric carcinoma cells." (PMID 29774127, 2018). "CDC73 mRNA expression was positively related to both overall and progression-free survival rates of the patients with gastric cancer, even stratified by gender, lymph node involvement, or treatment (p<0.05)." (PMID 29221126, 2017). "We collected the results from DErrico’s, Cho’s, Chen’s, Wang’s, and TCGA's datasets and analyzed CDC73 mRNA expression in gastric cancer." (PMID 29221126, 2017). "In gastric cancer, we found a positive correlation of CDC73 mRNA expression with both overall and progression-free survival rates, even stratified by gender, lymph node involvement, or treatment." (PMID 29221126, 2017).
Renal cyst (4 papers, 2016 to 2025). A fluid filled sac in the kidney. "No genotype-phenotype correlation has been reported for Wilms tumor and renal cysts in the context of CDC73 germline mutation." (PMID 33716975, 2021). "Renal cysts are also reported to be part of the clinical spectrum of HPT-JT and CDC73 germline mutation." (PMID 33716975, 2021).
acromegaly (3 papers, 2020 to 2024). Acromegaly is an acquired disorder related to excessive production of growth hormone (GH) and characterized by progressive somatic disfigurement (mainly involving the face and extremities) and systemic manifestations. "A CDC73 heterozygous missense mutation (Leu380Phe) was identified in a single patient within the Acropara group who presented with acromegaly, mild PHP, and developed a pancreatic NET, with no known family history of endocrine tumors." (PMID 32311048, 2020). "Sixteen patients with acromegaly and PHP underwent rigorous genetic testing with DNA sequence analysis performed for genes including: MEN1, CDC73, CDKN1A, CDKN1B, CDKN2B, CDKN2C, and AIP, as well as MLPA to search for deletions or duplications in MEN1, CDC73, CDKN1B, and AIP genes." (PMID 32311048, 2020).
adenofibroma (3 papers, 2017 to 2025). A benign neoplasm characterized by the presence of connective tissue stroma and epithelial structures. "In addition, a high proportion of women with CDC73 variants were found to have various types of uterine abnormalities (adenosarcoma, adenofibroma, leiomyoma, adenomyosis, and endometrial hyperplasia)." (PMID 39677927, 2025).
adenosarcoma (3 papers, 2019 to 2025). A low grade malignant neoplasm characterized by the presence of a benign epithelial component (tubular and cleft-like glands) and a low grade sarcomatous component that contains varying amounts of fibrous and smooth muscle tissues. "Our findings further substantiate the association between germline CDC73 variants and the infrequent development of adenosarcoma." (PMID 39594770, 2024). "Benign and malignant uterine involvement (including leiomyomas, endometrial hyperplasia, adenomyosis, multiple adenomyomatous polyps, and adenosarcomas) is the second most common clinical feature of the syndrome, affecting more than 50% of CDC73-carrier women." (PMID 31929790, 2019).
lung carcinoma (3 papers, 2017 to 2022). "In TCGA database, CDC73 mRNA was inversely linked to favorable overall prognosis of lung cancer, which was determined by its positive association with aggressive parameters." (PMID 29221126, 2017). "In contrast, there was positive association between CDC73 mRNA expression and post-progression survival rate of the patients with lung cancer according to KM plotter (p<0.05)." (PMID 29221126, 2017). "KRAS-driven and only bioinformatic analysis of the TCGA database shows that CDC73 mRNA expression was positively correlated with distant metastasis and unfavorable prognosis of lung cancer." (PMID 36430528, 2022). "CDC73 mRNA was more expressed in male than female patients with lung cancer (p<0.05)." (PMID 29221126, 2017). "According to TCGA database, CDC73 mRNA expression was positively correlated with distant metastasis, TNM staging, and unfavorable prognosis of lung cancer (p<0.05)." (PMID 29221126, 2017). "CDC73 mRNA expression was stronger in gastric intestinal- than diffuse-type carcinomas (p<0.05), and positively correlated with distant metastasis and TNM staging of lung cancer (p<0.05)." (PMID 29221126, 2017).
ovarian carcinoma (3 papers, 2014 to 2022). A malignant neoplasm originating from the surface ovarian epithelium. "We performed bioinformatics analysis of CDC73 mRNA expression in ovarian cancer using TCGA's and Hou's datasets." (PMID 29221126, 2017). "As for ovarian cancer, the prognostic significance of CDC73 expression was dependent on pathological grouping." (PMID 29221126, 2017). "It was found that CDC73 mRNA was overexpressed in gastric, lung, breast and ovarian cancers, even stratified by histological subtypes (p<0.05)." (PMID 29221126, 2017). "The prognostic significance of CDC73 mRNA was dependent on the datasets and pathological grouping in lung and ovarian cancers." (PMID 29221126, 2017). "In the present study, we aimed to explore the clinicopathological roles of CDC73 mRNA expression in various cancers using bioinformatics analysis, including gastric, lung, breast and ovarian cancers." (PMID 29221126, 2017). "However, a positive correlation between CDC73 expression and post-progression survival rate was observed in the patients with stage-IV ovarian cancer (p<0.05)." (PMID 29221126, 2017). "At mRNA level, CDC73 hypoexpression was detectable in colorectal, lung and ovarian cancers by real-time RT-PCR or in situ hybridization, but CDC73 mRNA was found to up-regulated in gastric, lung, breast and ovarian cancers by transciptomic sequencing in the present study." (PMID 29221126, 2017). "The data from KM plotter showed a negative relationship between CDC73 mRNA expression and either overall or progression-free survival rates of the patients with ovarian cancer (p<0.05)." (PMID 29221126, 2017).
renal tumors (3 papers, 2017 to 2025). "Screening for additional manifestations of CDC73-related disease in the proband was negative, including panoramic jaw X-rays and renal US done to evaluate for jaw and renal tumors, respectively." (PMID 39677927, 2025).
sarcoma (3 papers, 2021 to 2024). A usually aggressive malignant neoplasm of the soft tissue or bone. "Vice versa, all patients with a germline hit considered “second hit not expected” (in genes without a previously known association with mesenchymal tumors or sarcoma), except for CDC73 and ATM, had no second hit." (PMID 39594770, 2024). "Both germline and somatic hits were found in the ATM, CDC73, MLH1, MSH6, POLG, and KCNQ1 genes, which have no previously known connection with sarcoma." (PMID 39594770, 2024).
benign parathyroid tumors (2 papers, 2010 to 2012). "In the present study, we also assessed the value of HRPT2/CDC73 mutation screening and immunohistochemical analysis of parafibromin in the differential diagnosis of malignant and benign parathyroid tumors." (PMID 23029104, 2012). "In the present study, we identified six HRPT2/CDC73 mutations in 46.2% of cases with PC and none of those with benign parathyroid tumors." (PMID 23029104, 2012).
colon carcinoma (2 papers, 2023 to 2024). "To determine the mechanism underlying colon cancer stemness control by PAF1C, we further generated TetOff cells conditionally expressing amiRNAs against CDC73 and CTR9." (PMID 38182897, 2024).
lymph node metastasis (2 papers, 2017 to 2022). "The risk factors for lymph node metastasis in PC were investigated, including molecular biomarkers, such as CDC73 abnormalities and the Ki67 index." (PMID 36010997, 2022). "More importantly, we found that CDC73 abnormalities and high-risk Schulte staging were associated with lymph node metastasis." (PMID 36010997, 2022). "The risk factors for lymph node metastasis in PC were high-risk Schulte staging (p = 0.021) and CDC73 abnormalities (p = 0.012)." (PMID 36010997, 2022). "High-risk Schulte staging and CDC73 abnormalities could predict lymph node metastasis risk in PC patients." (PMID 36010997, 2022). "There was a negative association of CDC73 expression with the overall, relapse-free, and distant-metastasis-free survival rates of the cancer patients with no lymph node metastasis (p<0.05, data not shown)." (PMID 29221126, 2017).
oral squamous cell carcinoma (2 papers, 2020 to 2022). "At the transcriptional level, overexpression of Wilms’ tumor suppressor 1 (WT1) decreases CDC73 levels and promotes the proliferation of oral squamous cell carcinoma cells by binding to the CDC73 promoter." (PMID 36211470, 2022). "At the translational level, CDC73 can be targeted and inhibited by miR-182-3p, and its knockdown can reverse the suppressive effects of miR-182-3p inhibitor on the aggressive phenotypes of oral squamous cell carcinoma cells." (PMID 36211470, 2022).
pituitary adenoma (2 papers, 2021 to 2022). "Herein, one patient with AA presented with familial MEN1 syndrome characterized by AA and pituitary adenoma; the patient harbored two somatic CDC73 alterations (c.9_18delCGTGCTTAGC: p.Asp3Glufs∗15, c.571delG: p.Ala191Leufs∗11) but lacked MEN1 mutation." (PMID 33778063, 2021).
squamous cell carcinoma (2 papers, 2017). A carcinoma arising from squamous epithelial cells. "We found that a higher CDC73 expression in lung adenocarcinoma, large cell carcinoma and squamous cell carcinoma than that in normal lung tissues (p<0.05)." (PMID 29221126, 2017). "Evidence of inhibition of the CDC73 gene by a transcription factor or by a microRNA suppressing the CDC73 mRNA has been provided in squamous cell carcinoma but has yet to be confirmed for parathyroid neoplasia." (PMID 28774260, 2017).
aortic aneurysm (1 paper, 2014). A ruptured aneurysm located in the wall of the proximal portion of the descending aorta proceeding from the arch of the aorta. "In addition, two affected males had thoracic aortic aneurysms, which have not been previously reported to be associated with FIHP, HPT-JT, or CDC73 mutations, and it is possible that aortic aneurysms may be a novel feature of these disorders." (PMID 24823466, 2014).
Cachexia (1 paper, 2016). Severe weight loss, wasting of muscle, loss of appetite, and general debility related to a chronic disease. "Conditional knockout of both CDC73 alleles in E8.5 or older mice resulted in the retardation of embryonic growth and increased apoptosis, whereas in adult mice it resulted in cachexia and death within 20 days." (PMID 27658992, 2016).
esophageal cancer (1 paper, 2025). A primary or metastatic malignant neoplasm involving the esophagus. "CDC73 was upregulated in esophageal cancer, and its downregulation effectively hinders the proliferation and growth of esophageal cancer cells." (PMID 41318472, 2025). "For example, in esophageal cancer, CDC73 acts as a tumor-promoting factor." (PMID 41318472, 2025).
fibroma (1 paper, 2025). A non-metastasizing neoplasm arising from the fibrous tissue. "We describe a case of HPT-JT syndrome related to a CDC73 pathogenic variant, associated with a BT of the arm and a rare nonossifying fibroma of the mandible." (PMID 40568365, 2025). "We describe a case of HPT-JT syndrome related to a CDC73 pathogenic variant, associated to a brown tumor (BT) of the arm and a rare nonossifying fibroma of the mandible." (PMID 40568365, 2025).